COX15 (cytochrome c oxidase assembly factor COX15)
Description:
Catalyzes the second reaction in the biosynthesis of heme A, a prosthetic group of mitochondrial cytochrome c oxidase (CcO). Heme A is synthesized from heme B by two sequential enzymatic reactions catalyzed by heme O synthase (HOS) and heme A synthase (HAS). HAS catalyzes the conversion of heme O to heme A by two successive hydroxylations of the methyl group at C8, in a reaction that involves matrix ferredoxin and ferredoxin reductase. The first hydroxylation forms heme I, the second hydroxylation results in an unstable dihydroxymethyl group, which spontaneously dehydrates, resulting in the formyl group of heme A (By similarity).
Synonyms: HAS; CEMCOX2; MC4DN6
Tractability: Antibody: UniProt predicts a signal peptide or a membrane-spanning region. PROTAC: ubiquitination databases record sites on it; its protein half-life has been measured.
Target class: Enzyme; Oxidoreductase
Gene: Protein-coding gene on chromosome 10 (99,710,868 to 99,732,160, reverse strand). Ensembl gene ENSG00000014919.
Subcellular location: Mitochondrion inner membrane
Subcellular location (Human Protein Atlas): Mitochondria; Nucleoplasm
Pathways (Reactome):
Metabolism: Complex IV assembly; Heme biosynthesis
Gene Ontology:
Molecular function: oxidoreductase activity, acting on the CH-CH group of donors; protein binding; heme A synthase activity; heme binding
Biological process: cytochrome complex assembly; heme A biosynthetic process; heme biosynthetic process
Cellular component: cytochrome complex; mitochondrial inner membrane; mitochondrion; respiratory chain complex; membrane
Genetic constraint (gnomAD): Loss-of-function variants: 48 observed, 50.95 expected, observed/expected ratio (o/e) 0.94, 90% interval 0.75 to 1.2. The upper end of that interval is the gene's LOEUF score, 1.2, which puts it in group 5 of 6, group 1 being the genes least tolerant of losing a copy. Missense variants: 414 observed, 517.98 expected, observed/expected ratio (o/e) 0.8, 90% interval 0.74 to 0.87. Synonymous variants: 185 observed, 195.55 expected, observed/expected ratio (o/e) 0.95, 90% interval 0.84 to 1.07.
Gene-disease validity (ClinGen):
ClinGen rates the evidence that COX15 causes each of these diseases.
mitochondrial disease (autosomal recessive): Definitive.
Leigh syndrome (autosomal recessive): Limited. A progressive neurological disease defined by specific neuropathological features associating brainstem and basal ganglia lesions.
Homologues: Orthologues: chimpanzee COX15 (100% identical), macaque COX15 (98% identical), dog COX15 (93% identical), pig COX15 (92% identical), mouse Cox15 (90% identical), guinea pig COX15 (90% identical), rat Cox15 (90% identical), rabbit COX15 (76% identical), tropical clawed frog cox15 (73% identical), zebrafish cox15 (70% identical), Drosophila melanogaster CG3803 (51% identical), Caenorhabditis elegans cox-15 (46% identical).
Diseases named in the same sentence as COX15 in open-access papers:
COX15 is named in the same sentence as 25 diseases in open-access papers, as found by Europe PMC text mining. Sharing a sentence is not in itself a finding about the gene and the disease. The quoted sentences say what the papers report.
Leigh syndrome (5 papers, 2007 to 2024). "Mutations in COX15 trigger a complex IV deficit with subsequent infantile cardioencephalopathy that resembles Leigh syndrome." (PMID 38139332, 2023). "There is also a single case of a long surviving Leigh syndrome patient resulting from compound heterozygous mutations leading to S152* and S344P substitutions in Cox15." (PMID 33238568, 2020). "Pathogenic mutations in COX10 and COX15 are associated with Leigh syndrome, cardiomyopathy, and encephalopathy, among others, and, typically, such patients have an early fatal outcome due to respiratory failure." (PMID 33238568, 2020). "Of note, modeling of the R217W Leigh syndrome (LS)-associated substitution in yeast revealed the mutation affects oligomeric properties of Cox15." (PMID 32121449, 2020). "In fact, defects in the cox15 gene have resulted in heme a deficiencies whereas defects in COX function have lead to the onset of degenerative diseases such as Leigh syndrome and encephalohepatopathy." (PMID 17945021, 2007).
Mitochondrial myopathy (3 papers, 2019 to 2023). "In this muscle-specific Cox15−/− model, BZ worsened the mitochondrial myopathy." (PMID 30925787, 2019).
cardiomyopathies (2 papers, 2017 to 2019). "Compound heterozygous or homozygous missense mutations in COX15 have been identified in patients presenting with cardiomyopathy and/or encephalopathy, but not skeletal myopathy." (PMID 30530468, 2019).
developmental delay (2 papers, 2019 to 2023). "Patient 52F with developmental delay and microcephaly was found to have a pathogenic variant in the COX15 gene detected at an AAF of 12%." (PMID 31349857, 2019). "For example, PAVS contains a disease-associated variant of the COX15 gene (cc.750+85A>G), reported for a patient and responsible for a set of phenotypes including “Amblyopia”, “Bilateral basal ganglia lesions”, “Generalized hypotonia” and “Global developmental delay”." (PMID 37479972, 2023).
Alzheimer disease (1 paper, 2020). A progressive, neurodegenerative disease characterized by loss of function and death of nerve cells in several areas of the brain leading to loss of cognitive function such as memory and language. "COX15, one of the upregulated complex IV genes, is a key enzyme involved in heme-a biosynthesis and the over-expression of COX15 has been linked to the development of Alzheimer’s disease." (PMID 33287280, 2020).
leukemia (1 paper, 2022). A malignant (clonal) hematologic disorder, involving hematopoietic stem cells and characterized by the presence of primitive or atypical myeloid or lymphoid cells in the bone marrow and the blood. "To validate the function of SETD1A target genes (COX15, HMBS, UROS, RRNAD1, NUDT18, GSTZ1, HINT2, and COX18) in leukemia cells, we performed a CRISPR-based competitive cell proliferation assay in doxycycline-inducible Cas9-expressing MOLM-13 leukemia cells." (PMID 36450243, 2022). "We found a strong dependency for COX15, HMBS, and UROS in leukemia cells." (PMID 36450243, 2022). "The downregulation of COX15 expression by SETD1A disruption is also observed in non-MLL-r leukemia cell lines (U937 and K562) as well as sarcoma cell lines (A673 and RH30)." (PMID 36450243, 2022).
microcytic anemia (1 paper, 2023). Anemia in which the red blood cell volume is decreased. "COX15 is involved in the synthesis of heme a from heme b, while STEAP3 is iron transporter and its deficiency is associated with hypochromic microcytic anemia." (PMID 36836934, 2023).
myopathy (4 papers, 2018 to 2022). A disease of the muscle in which the muscle fibers do not function properly. "Contrary to the expectation, these mice had a reduced lifespan and worsened myopathy, compared with the control COX15-deficient mice." (PMID 35010981, 2021). "A similar response has been obtained in a mouse model where myopathy was caused to defective Cox15." (PMID 35922766, 2022). "Interestingly, transgene of alternative oxidase (AOX), bypassing respiratory complexes III and IV by transferring electrons from reduced ubiquinone directly to O2, into skeletal muscle-specific COX15-deficient mice with severe myopathy, resulted in decreased ROS through avoiding RET." (PMID 35010981, 2021). "Cox15 oxidizes the C8‐methyl group of heme O during the biosynthesis of the cytochrome c oxidase (cIV, COX)‐specific heme A. Cox15sm/sm mice are characterized by profound COX deficiency, leading to severe myopathy." (PMID 30309855, 2018).
cancer (3 papers, 2022 to 2025). A tumor composed of atypical neoplastic, often pleomorphic cells that invade other tissues. "In addition, qPCR confirmed that many NDD-related genes, such as CAMKMT, COX15, and GAS7 involved in neurodevelopment and cancer, were downregulated in the patients." (PMID 37664546, 2023).
degenerative diseases (2 papers, 2007 to 2018). "Oxidative phosphorylation genes specific for HCHWA-D, i.e., not represented in the other neurodegenerative disease categories were the ATP6V subunits, COX14, COX15, LRPPRC, and TCIRG1." (PMID 29706885, 2018).
COX15 also shares sentences with these, for which no sentence is quoted: Encephalopathy (2 papers); amblyopia (1); breast carcinoma (1); chronic myeloid leukemia (1); encephalomyopathies (1); hypertrophic cardiomyopathy (1); lactic acidosis (1); microcephaly (1); neurodevelopmental disorder (1); polyposis (1); porphyria (1); sarcoma (1); Skeletal myopathy (1); status epilepticus (1); tumor (1).